MAT1A (methionine adenosyltransferase 1A)
Diseases named in the same sentence as MAT1A in open-access papers (continued):
Sharing a sentence is not in itself a finding about the gene and the disease.
tumor (26 papers, 2005 to 2026). "MAT1A functions as a tumor suppressor in cholangiocarcinoma, where its encoded protein acts as a co-repressor of E-box elements, inhibiting the expression of oncogenic genes like c-MYC, MAFG, and c-MAF." (PMID 39438468, 2024). "Dysregulation of MAT1A in tumor cells was associated with replication errors and genetic instability." (PMID 37628631, 2023). "Up-regulation of tumor MAT1A was independently associated with male gender, and inversely related to tumors over 5 cm." (PMID 37240447, 2023). "Lastly, association of MAT1A with drug resistant cell populations may also lead to new small molecule inhibitors capable of eliminating drug resistant cells that ultimately allow tumor relapse." (PMID 31600961, 2019). "To further elucidate the influence of MAT1A on tumor growth, we established xenograft tumor models in nude mice by subcutaneously injecting NCI-H1299 cells with MAT1A knockdown (shMAT1A) and negative control (shCtrl)." (PMID 39438468, 2024). "By accelerating CCND1 degradation through SKP2-mediated ubiquitination, MAT1A depletion disrupts the delicate balance between cell proliferation and apoptosis, thereby impairing tumor growth." (PMID 39438468, 2024). "After 79 days of monitoring, we observed a significant reduction in tumor growth in mice injected with MAT1A-knockdown cells compared to controls (p < 0.001)." (PMID 39438468, 2024). "Specifically, CCND1 knockdown partially reversed the stimulative effect of MAT1A overexpression on tumor growth in mice." (PMID 39438468, 2024). "The GNMT and MAT1A proteins were found exclusively in the cytoplasmic fraction of tumor and normal tissues." (PMID 34065390, 2021). "Among them, MAT1A exerted a tumor suppressor effect and can also be used as an independent prognostic factor (Cox coefficient = −0.258, p = 6.8 × 10−3)." (PMID 32998289, 2020). "To further investigate the role of MAT1A in tumor relapse following gemcitabine treatment, we overexpressed MAT1A in transient transfections of 5637 cells (5637MAT1A+) and compared the gemcitabine IC50 profile of these cells to mock transfected controls." (PMID 31600961, 2019). "Survey of patient tumor sections confirmed elevated levels of MAT1A in individuals who received chemotherapy." (PMID 31600961, 2019). "The short-term SAM supplementation significantly decreased the number of small tumor nodules, proliferating hepatocytes and the total DNA methylation level, while it increased expression of the tumor suppressor proteins Mat1a and p21." (PMID 29285212, 2017). "High Mat1a, as well as high SAM level, is a marker of quiescent differentiated hepatocytes; thus, Mat1a can be considered as a classical tumor suppressor in HCC." (PMID 29285212, 2017). "This tumor had the lowest Mat1a/Mat2a ratio among the tested murine HCCs, and thus was expected to have the most aberrant DNA methylation." (PMID 25918251, 2015). "In the current study, we show that FGF-dependent proliferation is mediated in part via AKT-dependent β-catenin activation in both hepatoblasts as well as in Mat1a−/–derived tumor initiating liver stem cells similar to that seen during liver bud formation." (PMID 23308088, 2012). "We observed a significant increase in the expression of MAT1A, suggesting that pravastatin has a protective effect against tumour progression." (PMID 22353776, 2012). "To maintain our Mat1a−/− cells as phenotypically as a tumor initiating epithelial stem cell line, we further enriched for CD133 and CD49f by MACS." (PMID 23308088, 2012). "HCC cells commonly exhibit an imbalance in the expression of the methionine adenosyltransferase (MAT) family, characterized by downregulation of the tumor-suppressive MAT1A and upregulation of the oncogenic MAT2A, resulting in abnormalities in the S-adenosylmethionine (SAM) synthesis pathway." (PMID 41293169, 2025). "It was reported that Foxm1 directly interacts with Mat1a, which is a tumor suppressor in the liver." (PMID 34539442, 2021).
tumor (continued). "In addition, prohibitin 1 (PHB1) plays a tumor-suppressive role and positively regulates MAT1A while suppressing c-Myc." (PMID 32998289, 2020). "In this study, we demonstrate that FGF7 and FGF10, likely through FGFR2IIIb, induce downstream β-catenin activation and its nuclear translocation in both post-liver bud embryonic hepatoblasts and Mat1a−/− tumor initiating stem cell line via AKT-dependent phosphorylation of Serine-552." (PMID 23308088, 2012). "A recent study suggested that MAT1A as a tumor suppressor in HCC could inhibit NF-κB activity." (PMID 39438468, 2024). "Restoration of MAT1A expression or reduction in the expression of transcription factors such as MafG can inhibit CCA growth in vivo, thereby establishing MATα1 as a tumor suppressor gene in CCA." (PMID 41513616, 2026). "The functional analyses conducted in our study, involving stable knockdown of MAT1A in NSCLC cell lines, revealed multifaceted effects on tumor behavior." (PMID 39438468, 2024). "HE, IHC staining and WB showed the expression of MAT1A, CCND1, proliferation marker Ki67 and glycolytic marker (ALDOC, HK2) in tumor tissues, emphasizing the regulation of MAT1A and CCND1 on NSCLC cells." (PMID 39438468, 2024). "In HCC, the expression level of MAT2A is greater than that of MAT1A, leading to lower SAM production and rapid tumor growth." (PMID 37781509, 2023). "Low expression of MAT1A and GNMT1 were confirmed in the tumor tissues as compared to those in the adjacent normal tissues (for MAT1A and GNMT, p < 0.0001 and p = 0.012, respectively, consistent with the results obtained from the web server." (PMID 35008908, 2022). "Data from GEPIA demonstrated MAT1A and GNMT expressions were significantly higher in the adjacent normal tissues (n = 160) than those in the HCC tumor tissues (n = 369) (p < 0.001)." (PMID 35008908, 2022). "MAT1A/MAT2A switch has been involved in RAS/ERK, IKK/NF-kB, PI3K/AKT, and NF-kB signaling up-regulation, leading to increase in tumor cell proliferation, cell survival, and micro-vascularization." (PMID 31073374, 2019). "Remarkably, MAT1A overexpression, or c-MYC, MAFG, or c-MAF inhibition in tumor cells dramatically inhibited their in vitro and in vivo growth." (PMID 28422055, 2017). "Notably, in HCC, the expression of MAT2A is more dominant than that of MAT1A, thereby leading to decreased SAM production and rapid tumor growth." (PMID 37781509, 2023). "Furthermore, miR-203 transfection induced an increase in the SAM content of transfected cells, probably dependent on the reduction of MAT1A/MAT2A switch, the latter being largely responsible for SAM levels restriction and increase in proliferation capacity of tumor cells." (PMID 31073374, 2019).
cancer (16 papers, 2008 to 2026). A tumor composed of atypical neoplastic, often pleomorphic cells that invade other tissues. "Interestingly, CD133+/CD45- oval cells isolated from methionine adenosyltransferase 1a (Mat1a−/−) deficient mice, a cell population that resemble cancer stem cells, show cell growth inhibition in response to TGF-β but appear to be resistant to its apoptotic effects." (PMID 23301029, 2013). "EV-MATα2 can lower MAT1A expression, the liver’s defense to metastasis, while promoting its own oncogenic activity; the freely secreted MATα2-t is critical for cancer cell survival in part by activating FAK and promoting its own expression." (PMID 41331630, 2025). "Given the emerging significance of MAT1A in cancer biology, our research delves into the unexplored realm of its potential role and mechanism in NSCLC, a malignancy with high morbidity and mortality." (PMID 39438468, 2024). "Amidst ongoing debates on the role and mechanisms of methionine adenosyltransferase 1A (MAT1A) in cancer, our study sheds light on its significance in NSCLC." (PMID 39438468, 2024). "In summary, our study not only identifies MAT1A as a prognostic marker for poor survival in NSCLC patients but also elucidates its mechanistic contributions to cancer progression." (PMID 39438468, 2024). "Recent research has shown a spotlight on MAT1A, particularly its involvement in the metabolism and progression of various cancer types." (PMID 39438468, 2024). "The IHC images clearly demonstrated a marked contrast, with weak positive signals in para-carcinoma tissues contrasting sharply with robust MAT1A staining in NSCLC tissues." (PMID 39438468, 2024). "The antisteatotic role of Mat1a inhibition has been an unexpected finding as downregulation of Mat1a has always been associated with NAFLD and cancer development." (PMID 35232994, 2022). "We suggest that MAT1A and WRN variants and PMS2 loss could contribute to the hereditary cancer predisposition phenotype observed in this family." (PMID 37628631, 2023). "Gemcitabine is a chemotherapeutic which relies on the highly proliferative nature of cancer cells to exert an anti-cancer effect, thus, we hypothesized that MAT1A overexpression could influence proliferative ability." (PMID 31600961, 2019). "DNA methylation, histone modifications, and the chromatin structure are profoundly altered in human cancers and future studies will further determine how MAT1A is involved in some of these processes to contribute to drug resistance, in bladder, and possible other types of cancer." (PMID 31600961, 2019). "Furthermore, MAT1A dysregulation increases homocysteine levels, promoting cancer progression." (PMID 37628631, 2023). "Therefore, we may speculate that inhibiting MAT1A function in cancer cells might be beneficial in enhancing drug responsiveness." (PMID 31600961, 2019). "However, future studies will need to address whether attempting to repress MAT1A in vivo can improve cancer outcomes." (PMID 31600961, 2019). "In our eight signature genes (ARL6IP4, ATP2A1, CRYAB, ELFN2, MAP2, MAT1A, ORC1, and POU4F1), prior research has elucidated the expression and function of several genes involved in the initiation and progression of cancer." (PMID 41567198, 2025). "Of particular interest is the interplay between MAT1A and the methylthioadenosine (MTA) pathway, disrupted in MTAP-deleted cancers." (PMID 39438468, 2024). "Additionally, ultrasensitive quantification of SAM-derived methyl groups will further elucidate differences in DNA, RNA, and histone protein methylation to provide insight into whether SAM-mediated epigenetic modifications through MAT1A provide cancer cells with a drug resistant phenotype." (PMID 31600961, 2019). "The MAT1A:MAT2A switch, which was accompanied with an increasing expression of MAT2B, results in decreasing SAM levels and facilitates cancer cell growth." (PMID 24098708, 2013).
cancer (continued). "Collectively, these findings underscore the essential partnership between MAT1A and CCND1 in orchestrating NSCLC glycolysis and tumorigenesis, providing novel insights into the molecular mechanisms underpinning this metabolic reprogramming in cancer." (PMID 39438468, 2024). "Our study indicated that restoring MAT1A and GNMT expression may suppress EEF1D expression that is potentially oncogenic in human cancer progression." (PMID 35008908, 2022). "This is the first study demonstrated that MAT1A and GNMT, the 2 key enzymes involved in methionine cycle, could potentially attenuate cancer progression via suppression of ribosome translation." (PMID 35008908, 2022). "The present study indicated that restoring MAT1A and GNMT expression may suppress EEF1D expression that is potentially oncogenic in human cancer progression." (PMID 35008908, 2022). "Further research will be needed to evaluate utility of MAT1A as a biomarker across other cancer types in tissues where MAT1A is not natively expressed, as an indicator of aggressiveness and/or relapse post treatment." (PMID 31600961, 2019). "Previous studies have shown that the ratio of the expression of MAT1A, an oncogene, to that of MAT2A is positively correlated with HCC survival, the conversion of MAT1A to MAT2A reduces the biosynthesis of S-adenosylmethionine (SAMe), providing favorable conditions for cancer cell growth." (PMID 41513616, 2026).
infection (5 papers, 2014 to 2024). The state of being infected such as from the introduction of a foreign agent such as serum, vaccine, antigenic substance or organism. "Intriguingly, we also noted a pronounced accumulation of cells in the G2 phase of the cell cycle in both cell lines following infection with the shMAT1A lentivirus (p < 0.001), hinting at a cell cycle arrest induced by MAT1A depletion." (PMID 39438468, 2024).
metabolic disorder (5 papers, 2013 to 2023). "Mammals encode a liver-specific isoenzyme, MAT1A, that is genetically linked with an inborn metabolic disorder of hypermethioninaemia, as well as a ubiquitously expressed isoenzyme, MAT2A, whose enzymatic activity is regulated by an associated subunit MAT2B." (PMID 23425511, 2013). "Twenty cases (17 male and 3 female patients) of AR-type MATD were diagnosed with persistently high plasma Met concentrations and compound heterozygous or homozygous variants of MAT1A without other pathogenic genes in this metabolic disorder." (PMID 36704196, 2022).
MAT1A also shares sentences with these, for which no sentence is quoted: chronic hepatitis (2 papers); metabolic dysfunction-associated steatotic liver disease (2); non-alcoholic steatohepatitis (2); virus infection (2); alcohol (1); atherosclerosis (1); cardiovascular disease (1); depression (1); experimental autoimmune encephalomyelitis (1); fibrosarcoma (1); inflammatory bowel disease (1); Insulin resistance (1); leukemia (1); lung adenocarcinoma (1); lung carcinoma (1); lung squamous cell carcinoma (1); prostate carcinoma (1); sarcoma (1); Stroke (1); viral hepatitis (1); vitamin B12 deficiency (1).